BRCC3 (BRCA1/BRCA2-containing complex subunit 3)
Diseases named in the same sentence as BRCC3 in open-access papers (continued):
Sharing a sentence is not in itself a finding about the gene and the disease.
pulmonary arterial hypertension (1 paper, 2025). Pulmonary arterial hypertension (PAH) is a group of diseases characterized by mean pulmonary artery pressure >20 mmHg and elevated pulmonary arterial resistance leading to right heart failure. "BRCC3 regulates the BMP signaling pathway and maintains pulmonary vascular homeostasis by deubiquitinating K472 and K475 sites of ALK2.BRCC3 deficiency exacerbates pulmonary arterial hypertension, and PPARγ agonists can partially alleviate its effects." (PMID 40385572, 2025).
renal cell carcinoma (1 paper, 2020). "The NR5A1-derived tumors showed 657 unique proteins that participate in Renal cell carcinoma (CRK, ELOB and PAK3) and Homologous recombination (ATM, BRCC3 and MRE11) among others." (PMID 33261069, 2020).
TKCR syndrome (1 paper, 2018). "Analysis revealed that candidate gene BRCC3 coincides with genetic loci recognized as a causative for TKCR syndrome." (PMID 30093884, 2018).
xeroderma pigmentosum (1 paper, 2022). Xeroderma pigmentosum (XP) is a rare genodermatosis characterized by extreme sensitivity to ultraviolet (UV)-induced changes in the skin and eyes, and multiple skin cancers. "Only BRCC3 (p-value log(−10) = 1.87), WRN (p-value log(−10) = 2.09), USP45 (p-value log(−10) = 1.52) and the xeroderma pigmentosum complementation group A (XPA; p-value log(−10) = 1.32) were significantly upregulated." (PMID 36010871, 2022).
tumor (18 papers, 2010 to 2025). "Functionally, UCA1 carried out an oncogenic role by regulating the miR-582-5p/BRCC3 signal to promote tumor progression." (PMID 37564930, 2023). "Our study reported a novel signaling pathway that UCA1 promoted tumor progression by regulating miR-582-5p/BRCC3." (PMID 37564930, 2023). "We show that depletion of the DUBs USP28 and BRCC3 induces positive proliferation phenotypes, suggesting that they have tumor suppressive functions." (PMID 30838976, 2019). "The mechanism of BRCC3 in promoting tumor progression was unclear." (PMID 37564930, 2023). "Moreover, the dissected neoplasms were embedded in paraffin and assessed by immunohistochemistry, finding that the expression of Ki67 was lower in the BRCC3–/– group." (PMID 34604222, 2021). "Another tumor (TCGA-CI-6624) had a contribution of 28% of SBS8, with two somatic missense variants in BRCA2 of unknown pathogenic effect, as well as one each in RAD51AP2 and BRCC3." (PMID 41194282, 2025). "Specifically, these mutations are located on five tumor suppressors (SDHA, RB1CC1, PTCH1, DMBT1, BCR) and eight proto-oncogenes (MERTK, CSF1R, MYB, ROS1, PCM1, FGFR2, MYH11, BRCC3) and have an allele frequency lower than 0.01 in the Genome Aggregation Database (GnomAD)." (PMID 33466296, 2021). "Next, the expression levels of BRCC3, ZEB1, E-cadherin and vimentin in tumor tissues were detected via immunohistochemistry." (PMID 38449391, 2024). "Among these genes we identified was BRCC3, a component of the BRCA1 complex that guards genome integrity and exerts tumor suppressive activity during cancer development." (PMID 37887275, 2023). "Besides, BRCC3 could activate NLRP3 inflammasome-dependent pyroptosis, which could then promote tumor progression." (PMID 37564930, 2023).
cancer (15 papers, 2015 to 2025). A tumor composed of atypical neoplastic, often pleomorphic cells that invade other tissues. "Immunoprecipitation assay is used to detect the interaction between breast cancer susceptibility gene 1/2-containing complex subunit 3 (BRCC3) andZEB1." (PMID 38449391, 2024). "ABRO1 as a scaffold for the interaction between NLRP3 and breast cancer susceptibility gene complex subunit protein 3 (BRCC3), acting synergistically with BRCC3 promotes the inflammatory activation of NLRP3 by regulating the deamination of NLRP3." (PMID 34381452, 2021). "Consistently, downregulation of BRCC3 and its complex members has been previously associated with a higher sensitivity to DNA damage inducing agents in other types of cancer." (PMID 31576005, 2020). "Furthermore, the BRCC3 gene encoding for the catalytic subunit of BRCA1-A complex is homozygously deleted in 5.40% of 2658 whole cancer genomes analysed by ICGC/TCGA due to an Xp22.2-linked retrotransposition event." (PMID 41006228, 2025). "The results indicated a significant upregulation of the BRCC3 expression level in the cancer tissue compared to the paired adjacent and normal bladder tissue." (PMID 34604222, 2021). "BRCC3 has been reported to be a procarcinogenic factor in other cancers." (PMID 38449391, 2024). "The expression of BRCC3 was primarily localized to the nucleus of cancer cells." (PMID 26024915, 2015). "Interestingly, the ZRSR2 gene locus is located close to BRCC3 and FANCB on the X chromosome and is homozygously deleted in 6.63% of all cancers through a LINE-1 element retrotransposition event occurring at Xp22.230,31." (PMID 41006228, 2025). "In all, this study demonstrates that BRCC3 can increase the stability of ZEB1, upregulate ZEB1 expression, and promote the proliferation, migration, invasion, EMT, and metastasis of TNBC cells, providing a new direction for cancer therapy." (PMID 38449391, 2024). "Putative cancer drivers with a propensity to carry clonal SCNAs were an android receptor gene, the RNA gene XIST, the BRCA1 binding partners RBBP7 and NCOA2, a BRCC3 metaloprotease unit of the BRISC complex and CSTF2 that prevents inappropriate RNA processing at sites of DNA repair." (PMID 26632267, 2015).
brain diseases (1 paper, 2024). "BRCC3 is involved in several brain diseases and plays a significant role." (PMID 38544474, 2024).
neurological disorders (1 paper, 2024). "BRCC3, the human homolog of BRCC36, is implicated in neurological disorders and plays a crucial role in neuroinflammation and pyroptosis." (PMID 38544474, 2024).
BRCC3 also shares sentences with these, for which no sentence is quoted: Fanconi anemia (3 papers); dilated cardiomyopathy (2); hemophilia A (2); triple-negative breast carcinoma (2); acute myeloid leukemia (1); asthma (1); atrial fibrillation (1); Azoospermia (1); cardiovascular disease (1); cleft palate (1); cryptorchidism (1); Duodenal stenosis (1); Gynecomastia (1); hemophilia (1); Hypertension (1); infection (1); inflammatory liver diseases (1); invasive ductal carcinomas (1); keloid (1); pulmonary hypertension (1); renal dysplasia (1); Sepsis (1); Torticollis (1); virus infection (1).